ZNF416 (zinc finger protein 416)
Description:
Acts as a mechanosensitive transcriptional activator in fibroblasts, regulating the expression of genes involved in proliferation, extracellular matrix synthesis, and contractility in response to increased matrix stiffness.
Synonyms: FLJ20557
Tractability: PROTAC: ubiquitination databases record sites on it.
Gene: Protein-coding gene on chromosome 19 (57,571,566 to 57,578,911, reverse strand). Ensembl gene ENSG00000083817.
Subcellular location: Nucleus
Subcellular location (Human Protein Atlas): Nucleoplasm; Nuclear speckles
Pathways (Reactome):
Gene expression (Transcription): Generic Transcription Pathway
Gene Ontology:
Molecular function: DNA-binding transcription activator activity; DNA-binding transcription factor activity, RNA polymerase II-specific; RNA polymerase II cis-regulatory region sequence-specific DNA binding; DNA-binding transcription factor activity
Biological process: fibroblast activation; fibroblast proliferation; regulation of transcription by RNA polymerase II; positive regulation of DNA-templated transcription; regulation of DNA-templated transcription
Cellular component: nucleus
Genetic constraint (gnomAD): Loss-of-function variants: 5 observed, 10.26 expected, observed/expected ratio (o/e) 0.49, 90% interval 0.25 to 1.02. The upper end of that interval is the gene's LOEUF score, 1.02, which puts it in group 4 of 6, group 1 being the genes least tolerant of losing a copy. Missense variants: 675 observed, 748.51 expected, observed/expected ratio (o/e) 0.9, 90% interval 0.85 to 0.96. Synonymous variants: 267 observed, 264.89 expected, observed/expected ratio (o/e) 1.01, 90% interval 0.91 to 1.12.
Homologues: Orthologues: chimpanzee ZNF416 (99% identical), macaque ZNF416 (95% identical). Paralogues in human: ZNF530 (47% identical), ZNF17 (46% identical), ZNF776 (45% identical), ZNF417 (41% identical), ZNF587 (41% identical), ZNF287 (38% identical), ZNF34 (37% identical), ZKSCAN7 (35% identical), ZNF547 (35% identical), ZNF527 (34% identical), ZNF852 (34% identical), ZNF214 (32% identical), and 38 more.
Diseases named in the same sentence as ZNF416 in open-access papers:
ZNF416 is named in the same sentence as 9 diseases in open-access papers, as found by Europe PMC text mining. Sharing a sentence is not in itself a finding about the gene and the disease. The quoted sentences say what the papers report.
pulmonary fibrosis (2 papers, 2022 to 2025). Chronic progressive interstitial lung disorder characterized by the replacement of the lung tissue by connective tissue, leading to progressive dyspnea, respiratory failure, or right heart failure. "However, the underlying molecular mechanism by which ZNF416 protects against pulmonary fibrosis in vivo and in vitro is still unclear and requires further exploration." (PMID 36371191, 2022). "Emerging evidence from in-depth studies on ZNF416 function reveals its critical role not only in pulmonary fibrosis but also potentially in other fibrotic diseases." (PMID 40176795, 2025). "In the present study, we investigated the function of ZNF416 as a matrix stiffness-regulated mechanosensitive regulator during pulmonary fibrosis." (PMID 36371191, 2022). "In this study, our results indicate that mechanosensitive ZNF416 is a potential molecular target for the treatment of pulmonary fibrosis." (PMID 36371191, 2022). "In this study, we observed that the expression of ZNF416 was upregulated in the fibrotic lesions of both human idiopathic pulmonary fibrosis (IPF) and silicosis." (PMID 36371191, 2022). "Our data suggest that ZNF416 is essential for fibroblast activation and pulmonary fibrosis progression." (PMID 36371191, 2022). "Following this, we used ZNF416 siRNA-loaded liposomes in fibrotic lung mice to investigate the function of ZNF416 in silica-induced pulmonary fibrosis in vivo." (PMID 36371191, 2022). "Most importantly, our results showed that using ZNF416 siRNA-loaded liposomes could alleviate pulmonary fibrosis in mouse fibrotic models, providing a promising antifibrotic target." (PMID 36371191, 2022). "Notably, administration of ZNF416 siRNA-loaded liposomes remarkably reversed established experimental mouse pulmonary fibrosis." (PMID 36371191, 2022). "Interestingly, we illustrated that ZNF416 was increased in silicosis samples and experimental mouse pulmonary fibrosis models." (PMID 36371191, 2022). "Furthermore, we utilized ZNF416 siRNA-loaded liposomes by the tail vein significantly to reverse the established pulmonary fibrosis induced by silica and bleomycin (BLM)." (PMID 36371191, 2022). "Strategies aimed at silencing ZNF416 could be a promising approach to fight against pulmonary fibrosis." (PMID 36371191, 2022). "Notably, administration of ZNF416 siRNA-loaded liposomes combined with TGF-β1 receptor inhibitor remarkably reversed experimental mouse pulmonary fibrosis." (PMID 36371191, 2022). "​Consistently, the administration of ZNF416 siRNA-loaded liposomes could also attenuate BLM-induced pulmonary fibrosis, which was evidenced by qRT-PCR, western blot, H&E, Masson trichrome and Sirius red staining, immunofluorescence and hydroxyproline assays." (PMID 36371191, 2022). "Additionally, we next addressed whether targeting ZNF416 could be an attractive strategy for attenuating pulmonary fibrosis." (PMID 36371191, 2022). "Therefore, ZNF416 siRNA-loaded liposomes could be a viable therapeutic approach for pulmonary fibrosis." (PMID 36371191, 2022). "To explore whether targeting ZNF416 could prevent further progression of established fibrosis in vivo, we used ZNF416 siRNA-loaded liposomes to treat silica- and BLM-induced mouse pulmonary fibrosis models." (PMID 36371191, 2022). "Additionally, co-administration of ZNF416 siRNA-loaded liposomes and SB431542 further attenuated experimental pulmonary fibrosis." (PMID 36371191, 2022). "Besides the synergy therapeutic effect in silica-induced pulmonary fibrosis, treatment with BLM instillation further demonstrated the potential synergy effect of ZNF416 siRNA-loaded liposomes and SB431542." (PMID 36371191, 2022). "To detect the synergistic effects of ZNF416 siRNA-loaded liposomes and TGF-β signaling in vivo, we made another intervention model by administration of ZNF416 siRNA-loaded liposomes and TGF-β1 receptor inhibitor SB431542 in silica and BLM-induced pulmonary fibrosis." (PMID 36371191, 2022).
coronary heart disease (1 paper, 2025). "Our experimental validation results demonstrate that the low expression of ZNF416 in the disease group suggested its potential role as a protective factor in diabetic retinopathy complicated with coronary heart disease." (PMID 40176795, 2025).
diabetes (1 paper, 2025). "ZNF416 plays a pivotal role in modulating gene expression, cell proliferation, and apoptosis, and likely impacts the progression of diabetes-related complications through its regulation of cellular metabolic processes and inflammatory responses." (PMID 40176795, 2025).
heart failure (1 paper, 2024). Inability of the heart to pump blood at an adequate rate to meet tissue metabolic requirements. "ZNF416 is a zinc finger nuclease associated with fibroblast activation, and COUPTFII, encoded by the gene NR2F2, has been reported to repress glucocorticoid transcriptional activity and alter cardiac metabolism in heart failure." (PMID 38768074, 2024).
silicosis (1 paper, 2022). Silicosis is a respiratory disease caused by breathing in (inhaling) silica dust. "High levels of ZNF416 were detected in the fibrotic lung sections of human IPF and silicosis, as well as matrix stiffness-stimulated fibroblasts." (PMID 36371191, 2022). "Immunohistochemical (IHC) analysis indicated higher expression of ZNF416 in the lung tissues of both IFP and silicosis patients, whereas little ZNF416 expression was found in the normal subjects." (PMID 36371191, 2022).
ZNF416 also shares sentences with these, for which no sentence is quoted: cancer (1 paper); diabetic retinopathy (1); idiopathic pulmonary fibrosis (1); tumor (1).